GPX4 (glutathione peroxidase 4)
Diseases named in the same sentence as GPX4 in open-access papers (continued):
Sharing a sentence is not in itself a finding about the gene and the disease.
selenium deficiency (12 papers, 2016 to 2025). A nutritional deficiency disease resulting from inadequate selenium levels in the body, which can lead to impaired function of selenoproteins essential for antioxidant defense and thyroid hormone metabolism. "The observation of prioritized GPX4 expression at the expense of low-hierarchy selenoproteins, such as glutathione peroxidase 1 under selenium deficiency, suggests that GPX4 plays essential roles in the prevention of membrane oxidation." (PMID 35204181, 2022). "Such selenoproteins are known to give way to those on top of the hierarchy (e.g., GPx4) in times of selenium deficiency." (PMID 27128937, 2016). "Selenium deficiency affects the expression of selenoenzymes such as GPx1, GPx2, and GPx4 and selenoproteins (i.e., Selenoproteins-P, SELENOP), which are involved in not only fetal reproductive development and the regulation of oxidative stress but also the overall DNA methylation pattern." (PMID 37233634, 2023). "Furthermore, selenium deficiency is found to impact GPX4 biosynthesis, and this can account for the reduced ferroptosis vulnerability and antioxidant ability among psoriatic cases." (PMID 36685512, 2022). "Although the Zn2+ storage protein MT3 was elevated without change to the zinc transporters ZnT1 or ZnT3, we showed that selenium deficiency could induce release of Zn2+ from stores, likely through a decrease of the selenoprotein GPX4 and a subsequent increase in lipid peroxidation." (PMID 34277682, 2021). "Therefore, we speculate that since the expression and function of SLC38A5 are drastically suppressed by niclosamide in TNBC cells, it would cause selenium deficiency due to impaired Se-Met delivery, which would then be expected to decrease the stability of GPX4 mRNA and hence its protein levels." (PMID 38539825, 2024). "During selenium deficiency, the activity of liver GPX1 in rats drops to 3% of its normal activity, whereas the activity of GPX4 is better maintained." (PMID 38990713, 2024). "Interestingly, several genes encoding selenoproteins (GPX1, GPX4, SELENON, SELENOM, SELENOF, SELENOW, SELENOT) were also downregulated, suggesting molecular evidence of selenium deficiency." (PMID 40459789, 2025). "During times of selenium deficiency, the expression of certain selenoprotein genes such as GPX1, GPX3, and selenoprotein W (SELENOW) are more sensitive and thus downregulated compared with “housekeeping” selenoproteins such as deiodinases (DIOs) and GPX4." (PMID 39270936, 2024). "However, even though GPX4 and TXNRD1 expression were both decreased after 72 h of selenium deficiency, there was no increase in NQO1 activity or protein under these conditions." (PMID 39456464, 2024).
ulcerative colitis (12 papers, 2020 to 2025). An inflammatory bowel disease involving the mucosal surface of the large intestine and rectum. "In this study, we demonstrated that PD effectively protects against DSS-induced ulcerative colitis both in vitro and in vivo, elucidating its potential mechanism through Nrf2/Slc7a11/Gpx4-dependent inhibition of ferroptosis signaling pathways." (PMID 39877390, 2024). "Ferroptosis-related genes, including GPX4, a key regulator of ferroptosis, were found to be upregulated in intestinal mucosal ILC3s from ulcerative colitis patients." (PMID 39300068, 2024). "Our study suggested that PD protects against DSS-induced ulcerative colitis via Nrf2/Slc7a11/Gpx4-dependent inhibition of ferroptosis signalling activation." (PMID 39877390, 2024). "Butyrate has been reported to ameliorate ferroptosis in ulcerative colitis by modulating the Nrf2/GPX4 signal pathway." (PMID 39070785, 2024). "Finally, analysis of gene expression in IBD patients revealed that GPX4 expression decreased in both colon and rectum biopsies of Crohn’s disease (CD) patients as well as in the rectum of ulcerative colitis (UC) patients compared to healthy controls." (PMID 39819335, 2025). "Butyrate could ameliorate ferroptosis in ulcerative colitis by modulating the Nrf2/GPX4 signal pathway and improving the intestinal barrier." (PMID 39070785, 2024). "Curculigoside inhibits ferroptosis in ulcerative colitis through the induction of GPX4." (PMID 37238692, 2023). "In this study, the expression of ferroptosis biomarker ACSL4 increased, the expression of GPX4 and FTH1 decreased, and the expression of HO-1 decreased in the PFOS group, results consistent with the study of Yeru Chen on the relationship between ferroptosis and ulcerative colitis." (PMID 36136468, 2022). "To investigate a role of reduced GPX4 activity and LPO in human IBD, we analyzed biopsy-derived IEC-enriched specimens from the lesional and non-lesional mucosa of CD and ulcerative colitis (UC) patients with active disease." (PMID 32286299, 2020).
chronic obstructive pulmonary disease (11 papers, 2020 to 2026). A chronic and progressive lung disorder characterized by the loss of elasticity of the bronchial tree and the air sacs, destruction of the air sacs wall, thickening of the bronchial wall, and mucous accumulation in the bronchial tree. "Specifically, low levels of GPx4 and GSH have been associated with the development of chronic obstructive pulmonary disease (COPD) and the insufficient antioxidant stress response of human bronchial epithelial cells when exposed to cigarette smoke." (PMID 40573184, 2025). "Recent studies have shown that this third alpha-class hypoxia inducible factor subunit can modulate oxidative stress and mitigate ROS-induced damage under hypoxic conditions in chronic obstructive pulmonary disease, by influencing pathways involved in redox biology, such as the activation of GPX4." (PMID 39851564, 2025). "It has been found that GPX4 depletion-induced ferroptosis occurs in chronic obstructive pulmonary disease (COPD) pathogenesis under cigarette smoke exposure." (PMID 32103754, 2020).
fibrosarcoma (11 papers, 2021 to 2025). A malignant mesenchymal fibroblastic neoplasm affecting the soft tissue and bone. "For example, in human fibrosarcoma cells, GPX4 utilizes GSH to eliminate lipid peroxides and plays an important role in counteracting ferroptosis, while depletion of GPX4 or GSH enhances the sensitivity of fibrosarcoma cells to Erastin-induced ferroptosis." (PMID 38700533, 2024). "For example, in mouse models, it can block the activity of GPX4 to promote ferroptosis and thus inhibit the growth of fibrosarcoma." (PMID 34996454, 2022). "To this end, we induced ferroptosis in murine (NIH3T3 fibroblasts) and human (HT-1080 fibrosarcoma) transformed cell lines by incubating with the canonical ferroptosis inducers RSL3 (GPX4 inhibitor) or erastin (system xc− inhibitor)." (PMID 35763128, 2022). "Recent studies using co-crystal structure assays combined with mutation assays in HT-1080 fibrosarcoma cells, suggest that the region around Cys66 also serves as a covalent binding site for RSL3 and ML162 on GPX4, indicating they have multiple binding sites on GPX4." (PMID 38844964, 2024). "After applying GAL to fibrosarcoma cells, it was found that it can be used as a ferroptosis inhibitor, which increases the viability of HT1080 cells with an RSL3 inhibitor, reduces the level of ROS and MDA lipids, and increases the expression of PTGS2 and glutathione peroxidase 4 (GPX4) mRNA." (PMID 38674891, 2024).
heart failure (11 papers, 2019 to 2025). Inability of the heart to pump blood at an adequate rate to meet tissue metabolic requirements. "In this study, we systematically explored, for the first time, the mechanism by which calycosin alleviates heart failure by inhibiting ferroptosis through the regulation of the Nrf2/SLC7A11/GPX4 signaling pathway." (PMID 39600362, 2024). "HACE1 knockdown led to decreased cell viability, increased PI-positive cells and iron concentration (p < 0.05), and reduced GPX4 expression (p < 0.05) in the in vitro heart failure model." (PMID 38070140, 2023). "In particular, aortic banding increased cardiac NOX4 expression and reduced cardiac GPX4 activity in animal models indicating that ROS and ferroptosis are likely involved in the process proceeding from hypertrophic cardiomyopathy to heart failure." (PMID 36980208, 2023). "In the DOX-induced heart failure model, the GPX4 expression is downregulated, triggering lipid peroxidation of the DOX-Fe2+ complex and inducing mitochondria-dependent ferroptosis." (PMID 36620630, 2022). "Dapagliflozin can improve heart failure by inhibiting oxidative stress and ferroptosis, and its mechanism may be related to the regulation of Nrf2/HO-1/GPX4 signaling pathway." (PMID 39874368, 2025). "Similarly, puerarin, a phytoestrogen with antioxidant properties was shown to reduce NOX4 expression and to increase GPX4 expression in the heart failure rat model." (PMID 36980208, 2023). "Thus, the identification of mechanisms by which MI suppresses the transcription of GPX4 might provide a novel therapeutic approach to protect cardiomyocytes from ferroptosis and to control heart failure upon MI." (PMID 31685805, 2019). "Puerarin, an antioxidant reagent, can alleviate heart failure by increasing FTH1 and GPX4 expression in H9C2 cells and aortic banding rats." (PMID 36620630, 2022).
Nephropathy (11 papers, 2020 to 2025). A nonspecific term referring to disease or damage of the kidneys. "A functional single nucleotide polymorphism (SNP) site of GPX4 (rs713041) was found to be associated with higher eGFR in French/Belgian patients and inversely associated with the prevalence of nephropathy in Brazilian patients." (PMID 36275902, 2022). "It has been reported that its agonist, paricalcitol, upregulates GPX4 expression levels to restore antioxidant defense capacity, significantly reducing ferroptosis in cisplatin-induced kidney damage." (PMID 40636672, 2025). "In conclusion, Sirt1 enhances the resistance of renal tubular epithelium to ferroptosis induced by CaOx crystals through the PGC‐1α/NRF2/GPX4 pathway, thereby reducing CaOx‐induced kidney damage and further crystal deposition." (PMID 39498889, 2024). "In IRI-induced kidney damage, upregulated miR-182-5p and miR-378-3p suppress the expression of SLC7A11 and GPX4 proteins." (PMID 40636672, 2025). "In contrast induced nephropathy (CIN), SIRT1 activated by calorie restriction was able to reduce kidney damage via the modulation GPX4." (PMID 40109363, 2025). "In vivo, administration of ox-Alb exacerbated doxorubicin-induced nephropathy, as indicated by the elevated BUN, creatinine, and proteinuria, and intensified renal ferroptotic responses, including altered GPX4 and ACSL4." (PMID 40649703, 2025).
pancreatitis (11 papers, 2020 to 2025). Inflammation of the pancreas. "It has been reported that reduced GPX4 levels in mice can accelerate the development of experimental pancreatitis." (PMID 40538500, 2025). "Recently, studies of pancreatic Gpx4 deletion revealed increased pancreatic injury, edema, and mortality following induction of pancreatitis." (PMID 40907666, 2025). "In animal models of azure-induced pancreatitis, mice with specific pancreatic GPX4 knockouts exhibited more severe symptoms." (PMID 39606246, 2024). "Animal experiments with the AP-1 inhibitor SR11302 showed that inhibition of AP-1 can increase the expression of GPX4, reduce the level of lipid peroxidation, and significantly improve pancreatitis." (PMID 36670963, 2022). "Recent studies have highlighted the suppression of ferroptosis as a potential therapeutic strategy for pancreatitis, possibly through enhancing antioxidant enzymes such as GPX4, promoting iron efflux or sequestration, and reducing pro-ferroptotic proteins like ACSL4." (PMID 41470786, 2025). "Moreover, an animal study revealed that a high-iron diet or the conditional knockout of glutathione Peroxidase 4 (GPX4) in the pancreas promoted experimental pancreatitis." (PMID 39606246, 2024). "The activation of AP-1 plays an important role in ethanol toxicity and taurocholate-induced pancreatitis, and whether the AP-1/GPX4 regulatory axis plays an important role requires further study." (PMID 36670963, 2022). "We next determined the effects of GPX4-mediated antioxidant response on experimental pancreatitis." (PMID 33311482, 2020). "However, the interaction between AP-1 and GPX4 in patients with pancreatitis is unknown and requires further research." (PMID 36670963, 2022). "Similarly, mice lacking Gpx4 exhibited more severe pancreatitis following cerulein infection or ethanol administration." (PMID 41142608, 2025).
periodontitis (11 papers, 2020 to 2025). An acute or chronic inflammatory process that affects the tissues that surround and support the teeth. "Although our data suggest that butyrate may trigger ferroptosis in PDLFs, a GPx4-deficient animal model should be further used to explore the role of ferroptosis in the periodontitis development." (PMID 33298848, 2020). "NRF2 and glutathione peroxidase 4 (GPX4) expression are lower in periodontal tissues of periodontitis mice model." (PMID 40736688, 2025). "Diabetic periodontitis aggravated periodontitis pathogenicity and inhibited the expression of GPX4 and SLC7A11 in alveolar osteocytes and resveratrol alleviated these effects." (PMID 37432277, 2023). "We found that the expression of SLC7A11 and GPX4 was suppressed in the periodontitis group, and curcumin significantly improved the expression of SLC7A11 and GPX4 verified by qPCR, Western blotting and IHC assay." (PMID 37372983, 2023). "In mice with periodontitis, ferroptosis induction (by using erastin) aggravated alveolar bone loss and further decreased NRF2, GPX4 expression and GSH content inducing ROS formation and inhibiting osteogenic differentiation of primary mouse mandibular osteoblasts." (PMID 40736688, 2025). "Collectively, these results revealed that Ssa could promote osteoclast ferroptosis by inhibiting the Nrf2/SCL7A11/GPX4 signaling pathway, which attenuated alveolar bone resorption in the rat model of periodontitis." (PMID 39114369, 2024). "The results showed reduced expression of GPX4 in both the gingiva and alveolar bone by immunofluorescence staining, consistent with a lower gingival Gpx4 level and higher Acsl4 and Ptgs2 levels by RT‒qPCR in the periodontitis group." (PMID 38670955, 2024). "This suggested that curcumin may exert its protective effect on periodontitis by inhibiting ferroptosis via the SLC7A11/GPX4 axis." (PMID 37372983, 2023). "Moreover, resveratrol also mitigated the periodontitis pathogenicity, restored the alveolar osteocyte number and morphology, and upregulated osteocytic expression of GPX4 and SLC7A11 in diabetic periodontitis mice." (PMID 37432277, 2023). "The IHC staining demonstrated a significantly decreased GPX4 and SLC7A11 expression in the periodontitis and Cur 50 group compared with the control group and the other curcumin group." (PMID 37372983, 2023). "Osteocytes cultured in diabetic periodontitis conditions also showed downregulated SLC7A11 and GPX4 mRNA expression." (PMID 37432277, 2023). "Inhibition of ferroptosis rescued the diabetic periodontitis condition-induced osteocyte cell death as well as diabetic periodontitis condition-inhibited expression of SLC7A11 and GPX4 in osteocytes." (PMID 37432277, 2023). "To further investigate the occurrence of ferroptosis in periodontitis, we tested the expression level of ferroptosis-markers such as ACSL4, SLC7A11, GPX4 and TfR1 in the gingival tissue." (PMID 37372983, 2023). "Moreover, ligature-induced periodontitis in mice treated with curcumin exhibited increased expression levels of SLC7A11 and GPX4 and decreased expression levels of ACSL4 and TfR1." (PMID 37372983, 2023). "We have presented evidence suggesting that ferroptosis is involved in the development and progression of ligature-induced periodontitis, and curcumin attenuates ferroptosis by decreasing the ROS and MDA accumulation and reversing the down-regulation of GPX4 and SLC7A11." (PMID 37372983, 2023). "GPX4 was not examined regarding periodontitis, yet; however, glutathione peroxidases in general are related to periodontal inflammation and thereby related to PD-associated oxidative stress." (PMID 35003389, 2021). "Thus, Ssa could decrease osteoclastogenesis to attenuate alveolar bone resorption in the rat model of periodontitis and attenuated bone loss by inhibiting the Nrf2/SCL7A11/GPX4 signaling pathway without osteoblast toxicity." (PMID 39114369, 2024).
steatosis (11 papers, 2012 to 2025). Increased lipid within the cytoplasm of cells. "GPX4-mediated ferroptosis is closely related to the progression of free fatty acid-induced steatosis." (PMID 40169542, 2025). "To investigate the specific mechanisms by which Insig2 regulates ferroptosis in steatosis hepatic I/R, we have identified a molecule—GPX4, which exhibited significant changes at both the transcriptional and protein levels from the sequencing data." (PMID 40169542, 2025). "NaB effectively protects against FFAs-induced hepatocytic steatosis by modulating ROS/GPX4-mediated ferroptosis, and exhibits synergistic effects combined with Fer-1." (PMID 38397738, 2024). "Overexpression of hsa_circ_0048179 attenuated this oleate/palmitate-induced steatosis via hsa_circ_0048179/miR-188-3p/GPX4 signaling." (PMID 33221744, 2020). "In contrast to GSTM2, GSTM1, GSTA4, and GPX4 which are up-regulated in the steatosis patients, GSTT1 is found to be down-regulated." (PMID 22969728, 2012). "GPX4 expression was decreased in liver tissues of mice fed with HFD; the knockdown of TRIM59 could elevate GPX4 expression and decrease steatosis." (PMID 36417114, 2023). "In conclusion, TRIM59 can promote MAFLD steatosis and ferroptosis by enhancing GPX4 ubiquitination, and inhibiting TRIM59 can effectively improve the MAFLD process, so TRIM59 may be a potential target for MAFLD treatment." (PMID 37867509, 2023). "Moreover, glutathione peroxidase 4 (GPX4) is up-regulated in the steatosis patients and catalyzes the formation of the oxidized form of glutathione (glutathione disulfide, GSSG) from glutathione (GSH)." (PMID 22969728, 2012). "TRIM59 promotes steatosis and ferroptosis in MAFLD by enhancing GPX4 ubiquitination, and inhibition of TRIM59 can effectively improve the process of MAFLD." (PMID 37867509, 2023). "In summary, our study revealed that TRIM59 could promote steatosis and ferroptosis in NAFLD via enhancing GPX4 ubiquitination." (PMID 36417114, 2023). "In L02 cells, the elevation of GPX4 markedly ameliorates the steatosis in the presence of oeTRIM59 or not." (PMID 36417114, 2023).